DTYMK (deoxythymidylate kinase)
Description:
Catalyzes the phosphorylation of thymidine monophosphate (dTMP) to thymidine diphosphate (dTDP), the immediate precursor for the DNA building block dTTP, with ATP as the preferred phosphoryl donor in the presence of Mg(2+).
Synonyms: CDC8; TMPK; TYMK; CONPM; PP3731
Tractability: Small molecule: a structure with a bound ligand is known; a high-quality ligand is known. PROTAC: ubiquitination databases record sites on it; its protein half-life has been measured; a small molecule that binds it is known.
Target class: Enzyme; Transferase
Gene: Protein-coding gene on chromosome 2 (241,675,742 to 241,686,944, reverse strand). Ensembl gene ENSG00000168393.
Subcellular location (Human Protein Atlas): Mitochondria
Pathways (Reactome):
Metabolism: Interconversion of nucleotide di- and triphosphates
Gene Ontology:
Molecular function: ATP binding; dTMP kinase activity
Biological process: dTDP biosynthetic process; thymidine biosynthetic process; dTTP biosynthetic process; dUDP biosynthetic process
Cellular component: mitochondrion; cytosol
Genetic constraint (gnomAD): Loss-of-function variants: 20 observed, 20.69 expected, observed/expected ratio (o/e) 0.97, 90% interval 0.68 to 1.4. The upper end of that interval is the gene's LOEUF score, 1.4, which puts it in group 5 of 6, group 1 being the genes least tolerant of losing a copy. Missense variants: 320 observed, 285.91 expected, observed/expected ratio (o/e) 1.12, 90% interval 1.02 to 1.23. Synonymous variants: 148 observed, 120.41 expected, observed/expected ratio (o/e) 1.23, 90% interval 1.08 to 1.41.
Homologues: Orthologues: chimpanzee DTYMK (100% identical), macaque DTYMK (96% identical), rabbit DTYMK (86% identical), guinea pig DTYMK (83% identical), pig DTYMK (83% identical), mouse Dtymk (81% identical), rat Dtymk (81% identical), dog DTYMK (69% identical), tropical clawed frog dtymk (66% identical), zebrafish dtymk (64% identical), Drosophila melanogaster CG5757 (45% identical). Paralogues in human: CMPK2 (22% identical).
Diseases named in the same sentence as DTYMK in open-access papers:
DTYMK is named in the same sentence as 61 diseases in open-access papers, as found by Europe PMC text mining. Sharing a sentence is not in itself a finding about the gene and the disease. The quoted sentences say what the papers report.
hepatocellular carcinoma (11 papers, 2021 to 2025). A malignant tumor that arises from hepatocytes. "Elevated DTYMK expression in tumours such as liver cell carcinoma (LIHC) and lung adenocarcinoma (LUAD) is associated with a poor prognosis." (PMID 40357400, 2025). "In line with our observations, KPNA2, DTL, BACE2 and DTYMK were previously found to be associated with tumour stage also in other cancers, including hepatocellular carcinoma or glioma." (PMID 36320118, 2022). "Deoxythymidilate kinase (DTYMK) has been identified as a putative oncogene associated with the incidence of hepatocellular carcinoma (HCC), but the mechanisms whereby it regulates this cancer type remain uncertain." (PMID 35004265, 2021). "There was a mutual mediation effect between Streptococcus sanguinis and the hypermethylation of the cg12570942 site of the DTYMK gene, which is a potential biomarker for hepatocellular carcinoma." (PMID 37260411, 2023). "A Previous study reported that the upregulation of DTYMK was correlated with unfavorable prognosis and the immune microenvironment in hepatocellular carcinoma." (PMID 36159971, 2022). "In hepatocellular carcinoma, DTYMK expression predicts prognosis and chemotherapeutic response and correlates with the immune infiltration." (PMID 34925365, 2021). "However, DTYMK has been most thoroughly investigated in the context of hepatocellular carcinoma (HCC) and lung adenocarcinoma, wherein researchers extensively assessed the impact of inhibiting DTYMK or its knockdown on cancer cell behavior." (PMID 39195238, 2024). "A previous study suggested that DTYMK might play an inhibiting effect on the immune microenvironment in the tumorigenesis of hepatocellular carcinoma." (PMID 36159971, 2022). "Additionally, knockdown of DTYMK expression suppressed cell proliferation while overexpression of DTYMK promote that in hepatocellular carcinoma (HCC) cell line." (PMID 35903153, 2022). "As a thymidylate kinase involved in nucleotide biosynthetic process, DTYMK could positively promote proliferation of hepatocellular carcinoma through regulating the cell cycle." (PMID 35812404, 2022). "In addition, we have verified the role of DTYMK in hepatoma cell lines, and the results were consistent with the conclusions of the in silico analysis of data in the public databases." (PMID 34049287, 2021). "In hepatocellular carcinoma (HCC), DTYMK has been noted to serve as prognostic and chemotherapeutic response biomarker and positively correlated with tumor immune infiltration." (PMID 35903153, 2022).
lung carcinoma (7 papers, 2014 to 2022). "DTYMK catalyzes dTTP biosynthesis as synthetically lethal with lkb1 deficiency in mouse and human lung cancer lines." (PMID 29100421, 2017). "Dtymk, encoding deoxythymidylate kinase, which catalyzes dTTP biosynthesis, is synthetically lethal with Lkb1 deficiency in mouse and human lung cancer lines." (PMID 24722523, 2014). "Our study also found that DTYMK is associated with immune in human lung cancer types." (PMID 36170019, 2022). "DTYMK deletion reduced the dTDP pool and markedly suppressed lung cancer cell growth under serine/threonine kinase 11 (LKB1)-deficient conditions." (PMID 35903153, 2022). "Meanwhile, LKB1 mutant lung cancers have deficits in nucleotide metabolism that confer hypersensitivity to DTYMK inhibition." (PMID 35812404, 2022). "To validate DTYMK function in tumor cells, we examined DTYMK expression in tumor cell lines of various origins (lung cancer including 95C, 95D, A549, and H1299; pancreatic cancer MIA PaCa-2; liver cancer HepG2)." (PMID 35903153, 2022). "Our study showed that DTYMK is closely correlated with immune cells, suggesting that DTYMK plays a critical role in lung cancer immunity." (PMID 36170019, 2022). "Functional studies identified pyrimidine metabolic rate–limiting enzymes DHODH and DTYMK as therapeutic targets in lung cancer." (PMID 32638267, 2020). "In vitro, knockdown of DTYMK suppressed cell migration of liver and lung cancer cells." (PMID 35903153, 2022). "Furthermore, we found that pyrimidine metabolic rate–limiting enzymes CAD, RRM2, DTYMK, TYMS, TK2, and NR5C2 were all associated with the clinical outcomes of lung cancer and liver cancer." (PMID 32638267, 2020). "Similarly, the Kaplan-Meier survival analysis showed that pyrimidine metabolic rate–limiting enzymes DTYMK, NT5C3, RRM1, RRM2, TK1, TYMS, and UCK2 were all associated with adverse prognosis in the lung cancer." (PMID 32638267, 2020). "And the pyrimidine metabolic rate–limiting enzymes DTYMK, NT5C3, RRM1, RRM2, TK1, TYMS, and UCK2 had particular values in lung cancer prognosis." (PMID 32638267, 2020).
liver cancer (6 papers, 2020 to 2022). An epithelial or non-epithelial malignant neoplasm that arises from the liver. "In a previous study, DTYMK expression positively correlated with the infiltration of Tfhs, Tregs and M0 macrophages in liver cancer." (PMID 35903153, 2022). "When we additionally assessed the expression of this gene in PHHs and in the Hep3B, PLC/PRF5, HepG2, SK-HEP1, Huh7, and SNU398 liver cancer cell lines, we found that DTYMK was similarly overexpressed in tumor cells relative to levels in healthy PHHs." (PMID 35004265, 2021). "Our experiment results indicated that the depletion of DTYMK inhibited liver cancer cell proliferation and invasion." (PMID 34049287, 2021). "The expression of deoxythymidylate kinase (DTYMK) is up-regulated in liver cancer." (PMID 36170019, 2022).
lung adenocarcinoma (4 papers, 2022 to 2025). A carcinoma that arises from the lung and is characterized by the presence of malignant glandular epithelial cells. "In this study, we investigated the role of DTYMK in lung adenocarcinoma and found that the expression of DTYMK in LUAD tissues was significantly higher than that of DTYMK expression in adjacent normal tissues." (PMID 36170019, 2022). "In conclusion, our data demonstrated that DTYMK was correlated with progression and immune infiltration, and could serve as a prognostic biomarker for lung adenocarcinoma." (PMID 36170019, 2022). "Finally, we determine that DTYMK regulated cell proliferation, cell migration, and cell cycle of lung adenocarcinoma in vitro." (PMID 36170019, 2022). "Higher expression of DTYMK predicted worse outcome in several cancer types such as liver hepatocellular carcinoma (LIHC) and lung adenocarcinoma (LUAD)." (PMID 35903153, 2022).
glioma (3 papers, 2021 to 2024). A benign or malignant brain and spinal cord tumor that arises from glial cells (astrocytes, oligodendrocytes, ependymal cells). "Furthermore, we found that six downregulated genes, including pLCE1, PRPS2, FH, ASL, DTYMK, and CTPS1 were significantly increased in high-grade glioma tissues (p < 0.001)." (PMID 38438374, 2024).
microcephaly (3 papers, 2021 to 2022). A congenital or acquired developmental disorder in which the circumference of the head is smaller than normal for the person's age and sex. "recently reported two brothers with microcephaly, hypotonia and severe intellectual disability showing compound heterozygous variants in DTYMK." (PMID 34918187, 2022). "For instance, mutations in DTYMK, the gene coding for thymidylate kinase (TMPK), cause severe microcephaly in human." (PMID 35346037, 2022).
uveal melanoma (3 papers, 2021 to 2024). A melanoma derived from melanocytes of the uveal tract. "Our hypothesis of the double hit into tumoral DNA metabolism as a possible therapeutic option in uveal melanoma was confirmed since combined targeting of DTYMK and PARP1 affected all tested cytophysiological parameters with the highest efficiency." (PMID 39195238, 2024). "Going further, the subcellular distribution of DTYMK and PARP1 in uveal melanoma cells was determined through immunocytochemical analyses." (PMID 39195238, 2024). "Since we observed the overexpression of DTYMK and PARP1 in tumors derived from patients with uveal melanoma, we decided to test the influence of inhibitors of these enzymes in the in vitro model." (PMID 39195238, 2024). "Higher DTYMK expression represented worse OS in cancers including ACC (p = 0.0088), LGG (p = 6.6e-07), LIHC (p = 1.4e-05), LUAD (p = 0.00057), mesothelioma (MESO) (p = 0.036), PAAD (p = 0.011), skin cutaneous melanoma (SKCM) (p = 0.0012) and uveal melanoma (UVM) (p = 1.7e-05)." (PMID 35903153, 2022). "Taken together, these results indicate the independent role of DTYMK and PARP1 in the pathobiology of uveal melanoma, regardless of BAP1 status." (PMID 39195238, 2024).
adrenocortical carcinoma (2 papers, 2022 to 2024). "Elevated DTYMK activity has been observed across several malignancies, encompassing breast cancer, adrenocortical carcinoma, renal clear cell carcinoma, bladder carcinoma, and thyroid cancer." (PMID 39195238, 2024). "In adrenocortical carcinoma (ACC), kidney chromophobe (KICH), kidney renal clear cell carcinoma (KIRC) and LUAD, stage IV tumor tissue was associated with higher expression of DTYMK compared to other stages." (PMID 35903153, 2022).
breast carcinoma (2 papers, 2022 to 2024). "DTYMK protein expression was reduced in breast cancer and clear cell renal cell carcinoma when compared with normal tissues." (PMID 35903153, 2022). "The discrepancy between DTYMK mRNA and protein expression might be attributed to a smaller sample volume in the CPTAC dataset (TCGA vs. CPTAC, breast cancer: 1084 vs. 125, renal cancer: 512 vs. 110)." (PMID 35903153, 2022).
colorectal cancer (2 papers, 2021 to 2022). A primary or metastatic malignant neoplasm that affects the colon or rectum. "On the contrary, DTYMK played a protective role in colorectal cancer." (PMID 35903153, 2022). "DTYMK expression was found upregulated in 5-fluorouracil-resistant derivatives, suggesting that DTYMK might be related to drug resistance in colorectal cancer cells." (PMID 34795209, 2021).
pancreatic adenocarcinoma (2 papers, 2021 to 2022). "Gene amplification of DTYMK was more common in cancers such as ovarian serous cystadenocarcinoma (OV), uterine carcinosarcoma (UCS), pancreatic adenocarcinoma (PAAD), LUAD, thymoma (THYM), and LIHC." (PMID 35903153, 2022).
Aicardi–Goutières syndrome (1 paper, 2022). "Lastly, DTYMK deficiency resembles Aicardi–Goutières syndrome (AGS), both at the clinical as at the pathophysiological level." (PMID 34918187, 2022).
bladder urothelial carcinoma (1 paper, 2022). "Significant augmentation of DTYMK expression was observed in 19 cancer types, including bladder urothelial carcinoma (BLCA), breast invasive carcinoma (BRCA), and cervical squamous cell carcinoma (CESC) etc.." (PMID 35903153, 2022).
Brain atrophy (1 paper, 2022). Partial or complete wasting (loss) of brain tissue that was once present. "White matter destruction and brain atrophy are shared phenotypic features of AGS and DTYMK deficiency." (PMID 34918187, 2022).
colon adenocarcinoma (1 paper, 2022). "DTYMK expression was increased in 19 cancer types including BLCA, CESC and colon adenocarcinoma (COAD)." (PMID 35903153, 2022).
colon cancer (1 paper, 2017). "Interestingly, upregulation of TYMS and DTYMK was observed in the 5-FU resistant colon cancer cells." (PMID 29100421, 2017).
diffuse large B-cell lymphoma (1 paper, 2022). "Intriguingly, DTYMK acted as a protective factor for OS of diffuse large B-cell lymphoma (DLBC) patients (p = 0.0092)." (PMID 35903153, 2022).
glioblastoma multiforme (1 paper, 2022). "The results from these two databases commonly revealed that DTYMK expression was elevated in BLCA, CESC, COAD, glioblastoma multiforme (GBM), head and neck squamous cell carcinoma (HNSC), LIHC, LUAD, LUSC, rectum adenocarcinoma (READ), STAD and UCEC." (PMID 35903153, 2022).
melanoma (1 paper, 2022). A malignant, usually aggressive tumor composed of atypical, neoplastic melanocytes. "High DTYMK expression has been previously linked to increased melanoma cell proliferation, and shorter distant metastasis‐free survival in early stage melanoma." (PMID 36320118, 2022). "We identified KPNA2, DTL, BACE2 and DTYMK messenger RNA (mRNA) upregulated in melanoma versus nevi tissues by unsupervised data mining (N = 175 melanoma, N = 20 normal skin, N = 6 benign nevi) and experimentally confirmed differential mRNA expression in vitro (N = 18 melanoma, N = 8 benign nevi)." (PMID 36320118, 2022). "In summary, we have identified KPNA2, DTL, BACE2 and DTYMK cfRNAs as potential pan‐tumour liquid biopsy markers for prognostic and therapy monitoring in melanoma independent of the mutational genotype." (PMID 36320118, 2022). "Next, plasma cfRNA samples from melanoma patients (N = 18) versus control plasma of healthy donors (N = 18) were used to determine gene expression levels of six gene candidates (KPNA2, DTL, BACE2, DTYMK, E2F3 and SLC25A13) that showed excellent diagnostic accuracy (AUC >90.0%) in tissue." (PMID 36320118, 2022). "Through the re‐analysis of single‐cell RNA‐Seq (sc‐RNA‐Seq) data derived from 31 melanoma patients, we found that KPNA2, DTL, BACE2 and DTYMK are not only expressed by melanoma cells, but also by non‐malignant cells such as endothelial cells, cancer‐associated fibroblasts (CAFs), and immune cells." (PMID 36320118, 2022).
mitochondrial DNA depletion syndrome (1 paper, 2020). The mitochondrial DNA (mtDNA) depletion syndrome (MDS) is a clinically heterogeneous group of mitochondrial disorders characterized by a reduction of the mtDNA copy number in affected tissues without mutations or rearrangements in the mtDNA. "DTYMK is a novel gene associated with mitochondrial DNA depletion syndrome and prognosis of HCC." (PMID 32391055, 2020).
prostate adenocarcinoma (1 paper, 2022). "We noticed that DTYMK expression was the lowest in C3 subtypes (inflammatory, high Th1 and Th17 infiltration) of human cancers, especially in BLCA, BRCA, ESCA, LUAD, LUSC, OV, PAAD, prostate adenocarcinoma (PRAD), READ, SARC, and STAD." (PMID 35903153, 2022).
renal carcinoma (1 paper, 2022). A carcinoma arising from the epithelium of the renal parenchyma or the renal pelvis. "DTYMK protein expression was decreased in breast and renal cancer, but it was increased in colon, lung, ovarian and uterine cancer." (PMID 35903153, 2022).
stomach adenocarcinoma (1 paper, 2022). "Notably, we shed light on the positive correlation between DTYMK expression and immune cell infiltration in several cancers, such as brain lower grade glioma (LGG) and LIHC, but negative correlation in others like LUAD and stomach adenocarcinoma (STAD)." (PMID 35903153, 2022).
viral infection (1 paper, 2021). "Interestingly, many of the candidate proteins have only limited functional links to viral infection and immune regulation and were not previously known to interact with NAs (e.g., c8orf88, DTYMK, KIF2A, PDAP1, PDIA5, TAOK1, TAOK2, and VRK1)." (PMID 34853303, 2021).